OTUB1 (OTU deubiquitinase, ubiquitin aldehyde binding 1)
Diseases named in the same sentence as OTUB1 in open-access papers (continued):
Sharing a sentence is not in itself a finding about the gene and the disease.
tumor (continued). "As a result, our data revealed that stable OTUB1 interference in KTC‐1 triggered the decreased volume and weight of tumour." (PMID 34773364, 2021). "Lately, DUB3, OTUB1, and USP27X have been identified as specific DUBs to stabilize Snail and play important roles in Snail-mediated tumor metastasis." (PMID 31998374, 2019). "Both OTUB1 and FOXM1 were highly expressed in tumor lesions relative to paratumorous tissues with statistically significant correlation (r=0.610, p<0.01)." (PMID 27167337, 2016). "In order to test the possible function of OTUB1 in the regulation of tumor growth in vivo, we generated PC3 cells that stably express a short hairpin (sh) RNA targeting OTUB1 expression or a scramble control shRNA." (PMID 25623341, 2015). "To study the potential role of OTUB1 in CRC, we first used IHC staining to analyze the expression of OTUB1 protein in 260 CRC patients who received tumor resection at the Sun Yat-sen University Cancer Center between January 1999 and December 2005." (PMID 25431208, 2014). "This functional divergence informs distinct therapeutic strategies: interventions targeting OTUB1 prioritize immunomodulation and migration inhibition, whereas USP7-focused therapies aim to restore tumor suppressor function and block pro-proliferative signaling." (PMID 40469292, 2025). "Increased OTUB1 expression in the tumor microenvironment influences cytokine secretion and matrix metalloproteinase (MMP) release, modifies the tumor microenvironment structure, and enhances endothelial cell migration and proliferation, thereby promoting angiogenesis." (PMID 40430059, 2025). "Consequently, OTUB1 increases c-MYC protein levels and the expression of c-MYC target genes including hexokinase-2, which increase glycolysis and tumor growth." (PMID 38264570, 2023). "Furthermore, OTUB1 depletion increases CD8+ T cell infiltration, elevates serum IFN-γ, and augments anti-tumor immune responses in mouse models." (PMID 37415977, 2023). "Both CRC tumor tissues and CRC cell lines exhibited promoted OTUB1 expression level." (PMID 35354355, 2022). "As a member of the deproteinized cysteine protease subfamily of the ovarian tumor domain (OTU), OTUB1 could stabilize the expression level of target protein and maintain its function by inhibiting ubiquitination degradation." (PMID 33537306, 2020). "Considering that FOXM1 is upregulated in many tumor types, and FOXM1 participates in RCC progression, OTUB1/FOXM1 axis may have broad role in tumor progression across multiple tumor types, especially in RCC." (PMID 32257108, 2020). "However, OTUB1 also performed crucially in TGF-β-mediated gene transcription and cellular migration, subsequently promote tumor migration through." (PMID 33240928, 2020). "DUB3, OTUB1, and USP27X have been identified as specific DUBs to stabilize Snail and play important roles in Snail-mediated tumor metastasis." (PMID 31998374, 2019). "Finally, we investigated how the effect of ERRα on OTUB1 promotes CRC cells migration, which is essential for tumor metastasis." (PMID 31737118, 2019). "A sole mutant KRAS A549 cell line had increased colony formation in response to OTUB1 overexpression; however, in vivo tumor growth of A549 was not affected upon OTUB1 overexpression." (PMID 26881969, 2016). "Previous studies have described other crucial genes targeted by OTUB1, such as SMAD2/3, ERα and c-IAP2, that could promote tumor progression." (PMID 27167337, 2016). "No other significant correlations were observed between the OTUB1 expression level and age, gender, tumor location, tumor size, chemotherapy, or preoperative carcinoembryonic antigen (CEA) expression level." (PMID 25431208, 2014). "We found that OTUB1 regulated vimentin in CRC cell lines, although vimentin expression in the tumor stromal cells of CRC tissues was not correlated with OTUB1 expression." (PMID 25431208, 2014). "While most studies support a pro-tumor role of OTUB1, the conclusion is not unanimous." (PMID 38264570, 2023).
tumor (continued). "Subsequent experiments further suggested that OTUB1 promoted CRC malignancy by enhancing protein stability of β-catenin, via inhibition of its protein degradation by UPP pathway, which indicated its crucial role in enhancement of CRC tumor cellular proliferative and chemo-resistant capabilities." (PMID 35354355, 2022). "However, how the deubiquitinases (CSN5, USP9X, USP21, OTUB1, and USP22) coordinatePD-L1 protein level in response to distinct tumor microenvironment signals remains unknown." (PMID 34741014, 2021). "The specific function of OTUB1/Cyclin E1 axis in vivo could not be fully explained by subcutaneous tumor related experiments." (PMID 33537306, 2020). "However, in LIHC tumor tissues, OTUB1 was not significantly related to immune cell marker genes compared with normal tissues." (PMID 33240928, 2020). "Besides, overexpression of OTUB1ΔN46 or OTUB1A/S/A failed to elevate tumor weight or to accelerate tumorigenesis as much as OTUB1 wild type (p<0.01)." (PMID 27167337, 2016). "Similarly, the in vivo xenograft model showed that overexpression of OTUB1 could accelerate the tumor growth speed and increase the tumor weight, which were both suppressed by knockdown of FOXM1 in spite of OTUB1 overexpression (p<0.01)." (PMID 27167337, 2016). "However, it is still not very clear the exact role of OTUB1 in CRC tumor formation and progression." (PMID 35354355, 2022). "(b) Direct target protein binding: OTUB1 suppressed ubiquitination of proteins (e.g., HIF-1α and RACK1) through non-catalytic binding, thereby driving tumor progression." (PMID 40469292, 2025). "Additionally, the results of expression analysis on the data of Chinese Human Proteome Project (CNHPP) (110 paired tumor and nontumor tissues of clinical early‐stage HCC) showed consistently upregulation of protein level of OTUs (including OTUD7B, OTUD6B, ALG13, OTUB1, OTULIN) in HCC tissues." (PMID 32328410, 2020).
infection (13 papers, 2017 to 2024). The state of being infected such as from the introduction of a foreign agent such as serum, vaccine, antigenic substance or organism. "This suggests that the early defect in immune activation of OTUB1-deficient DCs resulted in insufficient control of the parasite at the early stage of infection." (PMID 32024978, 2021). "In agreement with the in vivo data, both expression of OTUB1 and deletion of MLKL in OTUB1-deficient HepG2 cells reduced LDH release upon infection with Lm and stimulation with TNF." (PMID 33712742, 2021). "Upon infection, OTUB1 is induced by type I IFNs and is associated with RIG-I at the mitochondrial membranes, where it activates RIG-I by a double mechanism." (PMID 34835115, 2021). "Under normal circumstances, an infection of this nature results in profound hepatocyte apoptosis, however, mice with a conditional ablation of OTUB1 in liver parenchymal cells showed a shift from apoptotic to necroptotic cell death." (PMID 37409125, 2023). "The reduction of c-IAP1 in OTUB1-deficient hepatocytes resulted in diminished apoptosis, induction of necroptosis and ERK-dependent TNF production upon infection with Lm and stimulation with TNF, respectively." (PMID 33712742, 2021). "Both infection with Lm and stimulation with TNF significantly increased numbers of p-MLKL+ cells and the amount of p-MLKL per cell in OTUB1-deficient HepG2 cells as compared to OTUB1-sufficient HepG2 cells." (PMID 33712742, 2021). "On examining mTOR activity, we did not observe phosphorylation of 4EBP1 during the acute phase of infection although it was detected later on, thereby allowing Otub-1 expression and GRAIL degradation." (PMID 28114324, 2017). "Here, we addressed the role of the DUB OTU domain aldehyde binding-1 (OTUB1) in hepatocyte cell death upon both infection with the hepatocyte-infecting bacterium Listeria monocytogenes (Lm) and D-Galactosamine (DGal)/Tumor necrosis factor (TNF)-induced sterile inflammation." (PMID 33712742, 2021). "However, infection with Lm and stimulation with TNF strongly increased association of OTUB1 with c-IAP1 and deubiquitination of K48-linked polyubiquitin chains from c-IAP1, thereby reducing its degradation." (PMID 33712742, 2021). "NS1 could trigger OTUB1 proteasomal degradation at the later stages of infection, leading to the inhibition of IRF3 and NF-κB activation, and thus preventing the antiviral response." (PMID 34835115, 2021). "However, infection of lentiviral Otub1 markedly increased c-Maf protein level and rescued the expression of ITGB7." (PMID 32999280, 2020). "Indeed, cells treated with GW4869 neutral sphingomyelinase inhibitor, which interferes with exosome release, released a reduced amount of OTUB1 upon infection." (PMID 29158431, 2018). "In the absence of S. Typhimurium, there were active DUBs in the extracellular space, but infection affected the presence or activity of several DUBs; for instance, it led to an increase in active OTUB1 secretion, based on its reactivity with the ubiquitin-specific probe." (PMID 29158431, 2018). "Combined in vivo and in vitro experiments comprising mice lacking OTUB1 specifically in liver parenchymal cells (OTUB1LPC-KO) and human OTUB1-deficient HepG2 cells revealed that OTUB1 prevented hepatocyte necroptosis but not apoptosis upon infection with Lm and DGal/TNF challenge." (PMID 33712742, 2021). "An increased expression of CTLA-4 during the acute phase of infection may block mTOR activation, thus preventing protein translation, (including Otub-1) and leading to the maintenance of GRAIL expression with reduced T cell proliferation and cytokine production." (PMID 28114324, 2017). "However, evidence also indicates OTUB1 may promote anti-infection immunity." (PMID 38264570, 2023). "Among these, one group containing OTUB1, OTUB2, OTUD4, OTUD5, OTUD6B, and OTUD7B showed obvious upregulation 6 h post-infection, followed by downregulation 12 h post-infection." (PMID 37650650, 2023).
infection (continued). "During the acute phase of infection, we observed an increased expression of GRAIL with low Otub-1 and mTOR expression and activation in CD4 T cells." (PMID 28114324, 2017). "Unlike the cases in astrocytes and epithelial cells, OTUB1 is reported to activate NF-kB in dendritic cells upon infection or LPS (lipopolysaccharide) stimulation." (PMID 38264570, 2023). "In addition, we showed that high expression of CTLA-4 and low levels of IL-2 prevented mTOR activation and Otub-1 protein expression, and maintained GRAIL expression, which inhibited T cell proliferation during the acute phase of the infection." (PMID 28114324, 2017). "Furthermore, the lethal infection phenotype that was observed in mice lacking OTUB1 in the parenchymal cells was rescued by the administration of necrostatin-1s and by co-ablation of MLKL." (PMID 37409125, 2023). "Interestingly, in vitro infection with T. gondii resulted in similar parasite burdens in OTUB1-sufficient and OTUB1-deficient BMDCs with or without IFN-γ prestimulation, suggesting that OTUB1 does not interfere with the cell-intrinsic parasite killing mechanism in DCs." (PMID 32024978, 2021). "Upon infection, deletion of MLKL in OTUB1LPC-KO mice significantly reduced ALT and LDH levels as compared to OTUB1LPC-KO illustrating that necroptosis aggravated liver damage in the absence of OTUB1." (PMID 33712742, 2021).
bacterial infection (3 papers, 2021 to 2023). "S. enterica serovar Typhimurium-infected THP-1 cells were shown to produce exosomes with higher abundance of deubiquitinating enzyme OTUB1, thereby indicating the involvement of DUBs in bacterial infection." (PMID 37841261, 2023). "Collectively, OTUB1 is a hepatocyte-intrinsic factor inhibiting necroptosis upon bacterial infection and TNF-induced liver damage, respectively, thereby, protecting the host from lethal exacerbation of these inflammatory diseases." (PMID 33712742, 2021).
kidney disease (3 papers, 2012 to 2024). "In the Korean population, the SNP rs77459372 in OTUB1 is associated with uric acid levels, underscoring OTUB1’s role in kidney disease-related traits." (PMID 39500879, 2024). "Although the potential role of OTUB1 in kidney diseases has been increasingly recognized, its specific role in LN remains underexplored." (PMID 39500879, 2024).
gastrointestinal tumors (2 papers, 2020 to 2021). "Based on the regulation of both cell death and pro-inflammatory signaling pathways by OTUB1 we explored the in vivo function of hepatocyte-specific OTUB1 during bacterial hepatitis and acute liver injury induced by DGal/LPS and DGal/TNF." (PMID 33712742, 2021). "Above all, our study analyzed the efficacy of OTUB1 in immunization regulation and the prognosis of gastrointestinal tumors, but further mechanism research and clinical validation are still needed." (PMID 33240928, 2020). "The expression levels of OTUB1 mRNA in digestive tumors and normal tissues were compared with the Oncomine database." (PMID 33240928, 2020).
adenocarcinoma (1 paper, 2016). A common cancer characterized by the presence of malignant glandular cells. "OTUB1 mRNA expression was also significantly up‐regulated in about 50% of adenocarcinomas and about 80% of SCC compared to normal tissue samples." (PMID 26881969, 2016).
infectious disease (1 paper, 2021). A disorder directly resulting from the presence and activity of a microbial, viral, or parasitic agent in humans. "It will be of interest to explore in more detail the in vivo role of OTUB1 in other PRR-related signaling pathways, cell types, and infectious diseases." (PMID 32024978, 2021).
myopathies (1 paper, 2024). "Future research is required to fully understand the precise mechanisms and degree to which OTUB1-deficient myopathies are caused by ferroptosis dysregulation; investigating autophagy-mediated ferroptosis in muscle cells obtained from animal models will be essential to achieving this goal." (PMID 38977909, 2024).
OTUB1 also shares sentences with these, for which no sentence is quoted: esophageal cancer (4 papers); hepatocellular carcinoma (4); cervical cancer (3); melanoma (2); neurodegenerative disease (2); acute lung injury (1); Alzheimer disease (1); benign prostatic hyperplasia (1); benign tumours (1); brain ischemia (1); cerebellar ataxia (1); gastritis (1); IgA nephropathy (1); intrahepatic cholangiocarcinoma (1); liver (1); lung squamous cell carcinomas (1); neuroblastoma (1); oesophageal cancer (1); oral squamous cell carcinoma (1); osteoarthritis (1); pancreatic adenocarcinoma (1); Plasmodium vivax malaria (1); postmenopausal osteoporosis (1); pulmonary arterial hypertension (1); squamous cell carcinoma (1); Trypanosoma cruzi Infection (1); urothelial carcinoma of the bladder (1).